PDGFRB (platelet derived growth factor receptor beta)
Diseases named in the same sentence as PDGFRB in open-access papers (continued):
Sharing a sentence is not in itself a finding about the gene and the disease.
ovarian carcinoma (49 papers, 2006 to 2026). A malignant neoplasm originating from the surface ovarian epithelium. "Our results indicated that PDGFRB was upregulated in ovarian cancer and positively associated with FIGO stage." (PMID 33731124, 2021). "Besides, the expression levels of PDGFRA and PDGFRB were significantly associated with venous invasion and lymphatic invasion of ovarian cancer." (PMID 36199822, 2022). "Furthermore, statistical analyses indicated that PDGFRB expression wasn’t an independent prognostic factor in ovarian cancer but was positively associated with FIGO stage." (PMID 33731124, 2021). "Therefore, PDGFRB is associated with ovarian cancer progression." (PMID 33731124, 2021). "Studies have shown that TMEM119 facilitates the proliferation, invasion, and migration of ovarian cancer cells, potentially through the PDGFRB/PI3K/AKT signaling pathway." (PMID 41465326, 2025). "Taken together, obtained data suggested that fibronectin expression in ovarian cancer is dependent on PDGFRβ and that it is responsible for cell aggregation." (PMID 38010623, 2024). "Our results confirm that primary tumors that induce ascites accumulation, which in turn contain ovarian cancer cells and tumorspheres, express high levels of PDGFRβ." (PMID 38010623, 2024). "Altogether, our results demonstrate that ovarian cancer requires PDGFRβ for the formation of fully functional aggregates, which are able to disseminate through the peritoneal cavity and generate intra‐abdominal implants." (PMID 38010623, 2024). "We report that platelet‐derived growth factor receptor beta (PDGFRβ) is essential for fibronectin‐mediated cell clustering of ovarian cancer cells into tumorspheres." (PMID 38010623, 2024). "Overall, all these data indicated that when PDGFRβ is silenced or pharmacologically inhibited, ovarian cancer cells lose their capacity to aggregate in suspension and die." (PMID 38010623, 2024). "Collectively, all these observations suggested that PDGFRβ is necessary for ovarian cancer cell aggregation and tumorsphere formation, which was further validated in four different ovarian cancer 3D models." (PMID 38010623, 2024). "We report that platelet‐derived growth factor receptor beta (PDGFRβ) is essential for fibronectin‐mediated cell aggregation of ovarian cancer cells into tumorspheres." (PMID 38010623, 2024). "Consistently, more intense IHC staining of PDGFRA and PDGFRB was observed in normal ovarian tissues than in tumor tissues of ovarian cancer." (PMID 36199822, 2022). "By virtue of UALCAN analysis, we identified that the protein levels of PDGFRA and PDGFRB were significantly lower in tumor tissues of ovarian cancer than those in normal tissues." (PMID 36199822, 2022). "Previous studies have established the link between PDGFRB overexpression and a poor prognosis in patients with renal cell carcinoma, oral squamous cell carcinoma, ovarian cancer, and colorectal cancer." (PMID 36467505, 2022). "Compared with the respective normal tissues, the mRNA and protein levels of PDGFRA and PDGFRB were substantially lower in tumor tissues of almost all cancer types, including ovarian cancer." (PMID 36199822, 2022). "In line with previous reports, we observed that PDGFRA and PDGFRB were predominantly expressed in the tumor stroma of ovarian cancer but merely expressed in cancer cells." (PMID 36199822, 2022). "In order to further detect the relationship between TMEM119 and PDGFRB in ovarian cancer progression, we downregulated PDGFRB expression by RNA interference and found there was no significant change in both mRNA and protein expression level of TMEM119." (PMID 33731124, 2021). "TMEM119 can regulate proliferation, invasion, and migration in ovarian cancer cells via the PDGFRB/PI3K/AKT signaling pathway." (PMID 33731124, 2021). "We then analyzed the expression of PDGFRB protein and found that its levels were higher in ovarian cancer tissues." (PMID 33731124, 2021).
ovarian carcinoma (continued). "Taken together, these findings suggested that TMEM119 can function an upstream of PDGFRB to regulate ovarian cancer progression." (PMID 33731124, 2021). "CCK-8 and EdU experiments demonstrated that knockdown of PDGFRB significantly attenuated viability and proliferation of ovarian cancer cells." (PMID 33731124, 2021). "TMEM119 promoted proliferation, invasion and migration of ovarian cancer cells partially via upregulating PDGFRB." (PMID 33731124, 2021). "In three independent publicly available microarray datasets of ovarian cancer patients we found a significant correlation between higher levels of PDGFRβ and VEGFR2 gene expression and reduced overall survival." (PMID 29228656, 2017). "In conclusion, we demonstrated that platinum-resistant ovarian cancers are characterized by distinct upregulations of PDGFRβ and VEGFR2." (PMID 29228656, 2017). "Concerning PDGF receptors, high PDGFRb expression was found to be correlated with poor disease-free survival in pancreatic cancer and additionally colon and ovarian cancer patients." (PMID 27941651, 2016). "In the absence of PDGFRβ, ovarian cancer cells can be provided with fibronectin by cancer‐associated fibroblasts (CAFs) to generate chimeric clusters." (PMID 38010623, 2024). "Indeed, PDGFRβ has been described to be expressed in tumor cells as well as in the stromal component of ovarian carcinomas." (PMID 38010623, 2024). "Moreover, our results also place the reported LKB1‐NUAK1‐fibronectin pathway in ovarian cancer spheroids below PDGFRβ." (PMID 38010623, 2024). "Hence, our data indicate that PDGFRβ‐directed fibronectin expression in ovarian cancer cells allows them to aggregate with each other and generate compact, disseminative‐efficient tumorspheres." (PMID 38010623, 2024). "In the absence of PDGFRβ, ovarian cancer cells can be provided with fibronectin by cancer‐associated fibroblasts to generate chimeric spheroids." (PMID 38010623, 2024). "Furthermore, the mRNA levels of PDGFRA and PDGFRB in ovarian cancer patients with venous invasion were higher than those in patients without venous invasion." (PMID 36199822, 2022). "ROC analysis also demonstrated that PDGFD (AUC = 0.995), PDGFRA (AUC = 1.000), and PDGFRB (AUC = 0.997) could be a single significant parameter to discriminate between normal and tumor tissues of ovarian cancer." (PMID 36199822, 2022). "Studies have reported that PDGFRB is expressed in a high percentage of epithelial ovarian cancers." (PMID 33731124, 2021). "We also uncovered PDGFRB inhibitor GZD856 as a potential drug in ovarian cancer treatment." (PMID 33731124, 2021). "Downregulation of PDGFRB also inhibited invasive and migratory abilities of ovarian cancer cells." (PMID 33731124, 2021). "Knockdown of PDGFRB could inhibit proliferation, invasion and migration of ovarian cancer cells in vitro, disclosing that PDGFRB was involved in ovarian cancer progression." (PMID 33731124, 2021). "Interestingly, fibronectin was observed to change the distribution presented in 3D cultured CAFs and to be specifically localized at the limiting area between central CAFs and peripheral sh‐PDGFRB cells within the chimeric spheroids, which is indicative of its role in ovarian cancer cells adhesion." (PMID 38010623, 2024). "We postulated that PDGFRβ could be upstream of this axis during ovarian cancer cell aggregation." (PMID 38010623, 2024). "Hence, it stands to reason that PDGFRβ is responsible for ovarian cancer cell clustering." (PMID 38010623, 2024). "We first examined whether PDGFRβ conferred an enhanced proliferative rate to ovarian cancer cells." (PMID 38010623, 2024). "In fact, CAFs have been described to recruit ovarian cancer cells to generate cellular aggregates by PDGF‐BB secretion and stimulation of PDGFRβ expression in ovarian cancer cells." (PMID 38010623, 2024).
ovarian carcinoma (continued). "In ovarian cancer, PDGFB (P < 0.05), PDGFD (P < 0.05), PDGFRA (P < 0.001), and PDGFRB (P < 0.001) had a significant positive correlation with macrophage M2 infiltration, and PDGFA had a negative association with macrophage M1 infiltration (P < 0.01)." (PMID 36199822, 2022). "Despite lower expression in ovarian cancer than in normal tissues, patients with higher PDGFD, PDGFRA, and PDGFRB also had worse OS, PFS, and PPS in ovarian cancer." (PMID 36199822, 2022). "Notably, for PDGFRA and PDGFRB, epithelial cell proliferation, epithelial cell migration, positive regulation of cell adhesion, and angiogenesis were also highly enriched, suggesting that PDGFRA and PDGFRB might be critically involved in the metastasis of ovarian cancer." (PMID 36199822, 2022). "Therefore, it still requires further exploration to figure out whether TMEM119 upregulates the transcription of PDGFRB in ovarian cancer by interacting directly with transcription factors and by binding with ligands to transfer signal into the cytoplasm or by other potential mechanisms." (PMID 33731124, 2021). "We also utilized GZD856, a PDGFRA and PDGFRB inhibitor which suppresses proliferation of lung cancer, and observed that GZD856 effectively inhibit proliferation, invasion and migration of ovarian cancer cells." (PMID 33731124, 2021). "Four different CAF subsets identified by analyzing specific CAF markers (FAP, integrin β1/CD29, αSMA, S100‐A4/FSP1, PDGFRβ, and CAV1) have been reported and related to immune modulation in human breast and ovarian cancers." (PMID 32909687, 2020). "In our study, we identified the genes with a mutation frequency ranking in the top 5 of 100 PTK genes in EOC, namely, MST1R, INSR, RET, PDGFRB, and PTK7, among which we studied the overlooked oncogenic role of RET in ovarian cancer." (PMID 32293499, 2020). "To further validate our findings, we analyzed the relationship between PDGFRβ and VEGFR2 mRNA expression levels and outcome of ovarian cancer patients using the PrognoScan database." (PMID 29228656, 2017). "Our study demonstrates that two angiogenesis-related proteins, platelet derived growth factor receptor beta (PDGFRβ) and vascular endothelial growth factor receptor 2 (VEGFR2) are upregulated in platinum-resistant primary human ovarian cancer." (PMID 29228656, 2017). "Overall, we demonstrate that, regardless of its source, PDGFRβ‐induced fibronectin not only directs initial cell clustering but also maintains ovarian cancer cells together, allowing their survival within the ascitic fluid." (PMID 38010623, 2024). "Collectively, all these data indicated that, regardless of its source, PDGFRβ‐induced fibronectin directs ovarian cancer cell aggregation and cluster formation." (PMID 38010623, 2024). "Mechanistically, we observed that it could upregulate the expression of platelet-derived growth factor receptor beta (PDGFRB) and activate PI3K/AKT signaling pathway, thereby promoting the proliferation, invasion, and migration of ovarian cancer cells." (PMID 33731124, 2021). "Similarly, ovarian cancer cells cultured in 3D conditions are unable to generate spheroids upon sunitinib treatment, and neither do the ones that have PDGFRβ silenced by shRNA." (PMID 38010623, 2024). "In the areas of breast and ovarian cancer, CAF subtypes have been defined based on multicolor flow cytometry yielding the four subtypes depending on how they stained for the fibroblast markers FAP, CD29, αSMA, S100-A4, PDGFRβ, and CAV1, accumulating differently in different tumors." (PMID 37745296, 2023). "Additionally, mural cell markers, such as chondroitin sulfate proteoglycan 4 (Cspg4, also known as NG2), alanyl membrane aminopeptidase (Anpep, also known as CD13), and platelet-derived growth factor receptor beta (Pdgfrb), were upregulated in FOXC2-expressing ovarian cancer cells." (PMID 36230774, 2022).
ovarian carcinoma (continued). "Those ovarian cancer patients with high expression of PDGFRβ and VEGFR2 might particularly benefit from additional anti-vascular therapy such as anti-VEGF antibodies or novel tyrosine kinase inhibitors targeting PDGFR and VEGFR." (PMID 29228656, 2017). "Interestingly, we demonstrate here that in the absence of PDGFRβ in ovarian cancer cells, PDGFRβ‐expressing CAFs could provide fibronectin to sh‐PDGFRB cells to generate chimeric spheroids." (PMID 38010623, 2024). "Consequently, we evaluated their mRNA expression by real‐time PCR and discovered PDGFRβ mRNA levels to be the most elevated in AS‐OV cells and significantly increased in ovarian cancer ascites compared to those of nonovarian cancerous ascites samples, such as colorectal cancer (CRC)‐derived ascites." (PMID 38010623, 2024). "Besides, ovarian cancer patients with lymphatic invasion expressed higher mRNA levels of PDGFRA and PDGFRB, even though the difference in PDGFRB had no statistical significance." (PMID 36199822, 2022).
pulmonary fibrosis (49 papers, 2006 to 2026). Chronic progressive interstitial lung disorder characterized by the replacement of the lung tissue by connective tissue, leading to progressive dyspnea, respiratory failure, or right heart failure. "Given its involvement in fibrogenesis, PDGFRβ is emerging as a promising biomarker of disease activity in lung fibrosis and repair." (PMID 40664934, 2025). "Further exploration of the therapeutic effects of specific targeting of PDGFB or its receptor PDGFRB in lung fibrosis will be of interest." (PMID 38600524, 2024). "PDGFRB is a well-described tyrosine kinase that plays a major role in the development of pulmonary fibrosis." (PMID 35163504, 2022). "Lung tissues from patients with pulmonary fibrosis were examined for the expression of Notch1/PDGFRβ/ROCK1 using RT-qPCR, western blotting, and immunostaining." (PMID 30902967, 2019). "As the downstream effector of Notch1, the level of PDGFRβ has been shown to be potentiated in a mouse lung fibrosis model." (PMID 30902967, 2019). "As further substantiation, the administration of a Notch1 inhibitor in a mouse model of lung fibrosis inhibited the PDGFRβ/ROCK1 pathway, suppressed pericyte proliferation and differentiation, and alleviated the severity of fibrosis." (PMID 30902967, 2019). "The goals of this study were to investigate the role of the Notch1/PDGFRβ/ROCK1 signaling pathway in the pathogenesis of pulmonary fibrosis and to explore the possibility of treating fibrosis by targeting Notch1." (PMID 30902967, 2019). "Given its direct involvement in pericyte transition to myofibroblast, PDGFRβ-targeted imaging may provide complementary insights to FAP imaging in pulmonary fibrosis." (PMID 40664934, 2025). "PET imaging targeting PDGFRβ could improve disease monitoring, and provide new insights into pulmonary fibrosis progression." (PMID 40664934, 2025). "In addition, studies have shown that imatinib, as a PDGFRβ inhibitor, can inhibit the differentiation of pericytes into fibroblasts by blocking the PDGF‐BB/PDGFRβ signaling pathway, thus improving pulmonary fibrosis." (PMID 40371544, 2025). "The increased expression of PDGFRB suggests that patients with severe COVID-19 might benefit from an early nintedanib therapy to prevent pulmonary fibrosis following SARS-CoV-2 infection." (PMID 35163504, 2022). "Elucidating mechanisms which modulate PDGFRβ signaling will give a greater understanding of the process of vascular smooth muscle remodeling in the context of cardiovascular disease, and possibly other PDGFR signaling-driven processes such as cancer and pulmonary fibrosis." (PMID 23922991, 2013). "Moreover, 4 weeks after bleomycin treatment, there was a marked increase in lung fibrosis in Ctnnb1-knockout mice, as assessed by anti-PDGFRa, anti-PDGFRb, anti-collagen I, and anti-collagen IV immunofluorescence staining and Sirius red staining of lung sections." (PMID 41535251, 2026). "Platelet-derived growth factor receptor beta (PDGFRβ) is expressed in activated myofibroblasts across multiple organs, and in the lung, its expression overlaps extensively with alpha smooth muscle actin positive cells in fibrotic foci in mouse models of lung fibrosis." (PMID 29813125, 2018). "To substantiate the effect of the Notch1/PDGFRβ/ROCK1 axis on pericyte differentiation and pulmonary fibrosis, we generated a mouse pulmonary fibrosis model in which the Notch1 signaling pathway inhibitor DAPT was used as a treatment." (PMID 30902967, 2019). "In vivo detection of PDGFRβ activity by [68Ga]Ga-DOTA-Cys-ATH001 PET can thus have widespread utility for detection of key fibrogenic cell populations also in other indications, such as lung fibrosis, heart fibrosis and tumor stroma." (PMID 41389114, 2025). "In summary, αSMA/PDGFRβ-positive myofibroblasts should not be addressed as a homogeneous target cell type within pulmonary fibrosis." (PMID 37349733, 2023).
pulmonary fibrosis (continued). "Based on these data, we conclude that ITGA8 deletion from PDGFRβ+ stromal cells does not affect lung fibrosis in the bleomycin model." (PMID 29813125, 2018). "Though ITGA8 exhibits LAP-TGFβ binding similar to other alpha integrins in the family, expression of ITGA8 in PDGFRβ+ cells does not appear to have a major biological role in lung fibrosis." (PMID 29813125, 2018). "Our previous studies have validated PDGFRβ-targeted PET using the radiolabeled Affibody molecule Z09591 (also known in the literature as ATH001) for detecting fibrogenic cells in liver fibrosis models, suggesting its potential for translation to pulmonary fibrosis (PF) and other fibrotic diseases." (PMID 40664934, 2025). "Although to our knowledge no one has assessed lung fibrosis in the global KO, our results show that ITGA8 in PDGFRβ+ cells is dispensable in the bleomycin model." (PMID 29813125, 2018).
chronic myeloid leukemia (46 papers, 2004 to 2026). "We report a case of a 65-year-old man diagnosed with a ETV6::PDGFRB-translocated MLN, presenting as atypical chronic myeloid leukemia (aCML), who exhibited a brief response with development of resistance to imatinib." (PMID 41278291, 2025). "Imatinib is a very potent inhibitor of tyrosine kinases such as ABL kinase, chimeric oncoprotein BCR-ABL of chronic myeloid leukemia, transmembrane KIT receptors, PDGFRα, and PDGFRb." (PMID 37623504, 2023). "Other neoplastic myeloid conditions have been associated with monocytic abnormalities including juvenile myelomonocytic leukemia, chronic myeloid leukemia with p190 fusion, and myeloid neoplasm with rearrangements of PDGFRA, PDGFRB, FGFR1 and PCM1-JAK2." (PMID 34073699, 2021). "Dasatinib (Sprycel®) is an ATP-competitive inhibitor of BCR-ABL, ephrin (EPH), c-Kit, PDGFRβ, and Src family kinases and has been approved by the United States Food and Drug Administration (FDA) for the treatment of adult chronic myeloid leukemia (CML) and Ph+ acute lymphoblastic leukemia (ALL)." (PMID 29091939, 2017).